H2BC19P (H2B clustered histone 19, pseudogene)
Description:
Core component of nucleosome. Nucleosomes wrap and compact DNA into chromatin, limiting DNA accessibility to the cellular machineries which require DNA as a template. Histones thereby play a central role in transcription regulation, DNA repair, DNA replication and chromosomal stability. DNA accessibility is regulated via a complex set of post-translational modifications of histones, also called histone code, and nucleosome remodeling.
Synonyms: HIST2H2BD; H2B/s; H2B/o; H2BFO
Gene: Transcribed unprocessed pseudogene on chromosome 1 (149,843,041 to 149,843,533, forward strand). Ensembl gene ENSG00000220323.
Subcellular location: Nucleus; Chromosome
Diseases named in the same sentence as H2BC19P in open-access papers:
H2BC19P is named in the same sentence as 1 disease in open-access papers, as found by Europe PMC text mining. Sharing a sentence is not in itself a finding about the gene and the disease. The quoted sentences say what the papers report.
infertile (1 paper, 2023). "In fact, we have observed increased retention of histone proteins (H1-3, H1-4, H1-7, H2BC19P, H2BC11, H2BC12, H2BS1) in the spermatozoa of idiopathic infertile patients implying improper nuclear remodelling." (PMID 37261076, 2023).